RN7SL11P (RNA, 7SL, cytoplasmic 11, pseudogene)
Gene: Miscellaneous RNA gene on chromosome 6 (89,478,141 to 89,478,433, forward strand). Ensembl gene ENSG00000239316.
Homologues: Orthologues: chimpanzee Metazoa_SRP (99% identical), macaque Metazoa_SRP (89% identical). Paralogues in human: RN7SL2 (87% identical), RN7SL1 (86% identical), RN7SL3 (85% identical), RN7SL383P (84% identical), RN7SL498P (83% identical), RN7SL47P (83% identical), RN7SL509P (82% identical), RN7SL147P (82% identical), RN7SL220P (82% identical), RN7SL444P (82% identical), RN7SL242P (82% identical), RN7SL336P (82% identical), and 703 more.